TGFBR2 (transforming growth factor beta receptor 2)
Diseases named in the same sentence as TGFBR2 in open-access papers (continued):
Sharing a sentence is not in itself a finding about the gene and the disease.
tumor (continued). "This is consistent with our findings that reconstituted TGFBR2 expression in an MSI tumor cell line leads to less sialic acid incorporation on ß1-integrin, while the TGFBR2-deficient tumor exhibits increased sialylation." (PMID 23468914, 2013). "Deletion of Tgfbr2 in a variety of epithelial cells results in a more aggressive tumor phenotype in mammary, pancreatic, colon, intestinal, head and neck, anal and genital tumors (reviewed by Yang)." (PMID 23408900, 2013). "In the present work we have used this HCT116-TGFBR2 model system to characterize TGFBR2-dependent alterations of protein glycosylation in MSI tumor cells." (PMID 23468914, 2013). "In our MSI tumor cell line model system, sialylation of ß1-integrin turned out to be modulated by TGFBR2 expression and signaling and was dependent on de novo protein synthesis." (PMID 23468914, 2013). "We also confirmed that TGFBR2 expression is reduced in PCa, which is compatible with the tumor suppressor role of TGFBR2 in PCa cells described by others, but promoter methylation does not seem to be involved." (PMID 23185447, 2012). "In our study, tumours overexpressing VEGFA165 showed lower expression of TGFBR2 and higher expression of SMAD7, suggesting a resistance to the TGF-β-induced cell cycle arrest." (PMID 22045186, 2011). "Gene expression profiling revealed human genes involved in TGF-β signalling differentially expressed between both tumour groups, that is, TGFBR2 and SMAD5 were lower expressed whereas the inhibitory SMAD7 was higher expressed with VEGFA165." (PMID 22045186, 2011). "However, as commented by the authors, this hypothesis does not always hold true, since it is well recognized that MSI, which is known to cause inactivation of a number of tumor suppressors (including TGFBR2, BAX, and many others), is associated with better patient outcome." (PMID 22050898, 2011). "TGFB1 (transforming growth factor-β, TGF-β) and its receptor TGFBR2 constitute a signaling pathway that regulates the transcription of many genes, and functions as a tumor suppressor and an immune response regulator." (PMID 21949851, 2011). "Expression of the other two genes, FOS and TGFBR2, is reduced in tumor tissues, which is in agreement with the literature." (PMID 19087325, 2008). "Consistently, TGFBR2 knockdown restored CD4+ T cell anti‐tumour activity against DLBCL cells." (PMID 41492119, 2026). "Similarly, the TGF-β signaling pathway plays a pivotal role in tumor initiation and progression, with TGFBR2 serving as one of its core components." (PMID 40978038, 2025). "Moreover, TGFBR2 inhibition reverses this immunosuppressive tumor cell phenotype by reducing CD8+ T cell exhaustion and enhancing CD4+ and CD8+ T cell-mediated tumor cell killing." (PMID 40277917, 2025). "Furthermore, contrary to TGFBR2 loss, SMAD4 deletion in KPC and KvPC PDAC drove primary tumor growth in vivo." (PMID 39841099, 2025). "On the contrary, in L19 and M30, a frameshift variant and a stop gained variant, respectively, were detected in the TGFBR2 gene in the matched tumor tissue, but not in any of the plasma samples." (PMID 41044171, 2025). "In addition, disrupting the TGF-β pathway through TGFBR2 knockout has been shown to enhance NK cell–mediated tumor killing." (PMID 40315330, 2025). "Additionally, MSI-induced frameshift mutations in TGFBR2 disrupt TGF-β signaling, which normally functions as a tumor suppressor by regulating cell growth and differentiation." (PMID 40452892, 2025).
tumor (continued). "By combining the molecular manipulation of GBM cells, single-cell sequencing, computational analyses, and tumor-immune cell co-culture systems, we identify a novel TGFBR2-driven phenotype in GSCs with molecular parallels to regulatory T cell (Treg) fate induction." (PMID 40277917, 2025). "CD4+ and CD8+ T cells cultured in CM obtained from mGSCs pre-treated with ITD-1 or from TGFBR2-knockdown GBM cells displayed enhanced TCR-independent tumor cell-killing capacity compared to T cells cultured in either unconditioned medium or in CM from control mGSCs (DMSO-treated or no doxycycline)." (PMID 40277917, 2025). "Moreover, we orthotopically transplanted tumor organoids derived from TMP and TMPT nude mice into immune complete C57BL/6 mice to investigate the role of Tgfbr2 loss in immune evasion." (PMID 39049720, 2024). "This study found that when the Tgfbr2 gene, which is responsible for tumour growth, was suppressed in lung cancer cells, it led to the restructuring of the tumour microenvironment and enhanced tumour immune response." (PMID 39427211, 2024). "Additionally, a differential expression of the cytokine genes CCL2, CCL20, TGFB1, and TGFB2; the transcription factor gene IRF4; and the receptor genes CCR2, IL10RB, TGFBR1, and TGFBR2 was identified in tumor tissue and vestibular nerve tissue." (PMID 39272860, 2024). "Moreover, CD44, CXCL12 and TGFBR2 were positively correlated with all tumor infiltrating immune cells." (PMID 38877052, 2024). "TGFBR2 had a tumor-suppressive effect but its expression was suppressed by miR-301b-3p in BC cells." (PMID 39525474, 2024). "The present findings demonstrated that miR-301b-3p played a crucial role in promoting BC cell growth, invasion and migration and anti-apoptosis, and that targeting TGFBR2 could inhibit the tumor-promoting effect of miR-301b-3p." (PMID 39525474, 2024). "TGF-beta receptor II (TGFBR2) was a tumor suppressor in CRC." (PMID 37280630, 2023). "To determine whether TGF-β in myeloid cells alters the response to radiotherapy, we employed Tgfbr2-cKO and Tgfbr2fl/fl (hereafter WT) for tumor-growth experiments." (PMID 38099498, 2023). "cG7-sTGFBR2 is able to transport TGFBR2 into the tumor microenvironment by targeting CD24." (PMID 37484024, 2023). "Most studies have investigated the role of TGF-β signaling in tumor progression and immunoregulation using mice with Tgfbr2 depletion or expression of a dominant-negative form of Tgfbr2, which results in abrogation of any signal transduction induced by all three isoforms of TGF-β 20-23." (PMID 37781043, 2023). "Knockdown of TGFBR2 inhibits tumour angiogenesis by miR-204 modulation." (PMID 37333824, 2023). "Deletion of Tgfbr2 in mature CD4+ T cells using Thpok-Cre transgenic mice suppressed tumor outgrowth by relocation of CD4+Tgfbr2−/− T cells from their usual site in the tumor parenchyma to the tumor stroma." (PMID 36382146, 2022). "In conclusion, miR-17-5p and TGFBR2 play an essential role in tumor genesis and development." (PMID 35241117, 2022). "TGFBR2 frameshift mutations also result in the generation of possibly immunogenic neoantigens, TGFBR2 signaling impairment may also directly promote inflammation in the tumor microenvironment of CRC." (PMID 36531239, 2022). "Moreover, genetic mice with myeloid cell-specific depletion of Tgfbr2 display less tumor metastasis." (PMID 35720407, 2022). "Other studies have shown that the inhibition of the endogenous TGF-β receptor (TGFBR2) signal in CAR-T cells enhanced the anti-tumor function of ROR1-specific CAR-T cells against triple-negative breast cancer by reducing Treg conversion and also prevented the exhaustion of CAR-T cells." (PMID 36172343, 2022). "Correlation analysis showed that miR-17-5p and TGFBR2 correlated with tumor immunity." (PMID 35241117, 2022). "TGFBR2 exhibits a tumor suppressive function in ccRCC and attenuates TGFβ response." (PMID 35549739, 2022).
tumor (continued). "According to public databases, tumors harboring TGFBR2 mutations showed a greater degree of vascular invasion than tumors without such mutations, which contributes to tumor progression in MSI-positive CRC." (PMID 36430910, 2022). "The in vivo experiments implied that tumor growth under gefitinib may be regulated by the circ_MACF1/miR-942-5p/TGFBR2 axis." (PMID 34996416, 2022). "We obtained that circFAM120B regulated the miR-645/TGFBR2 pathway to limit tumor growth in vivo." (PMID 34381772, 2021). "Furthermore, IHC staining demonstrated that knockdown of circSEC24A remarkably reduced the expression of Ki-67, PCNA and TGFBR2 in xenograft tumor tissues." (PMID 34906151, 2021). "TGFBR2-edited CAR T cells had better in vivo tumor elimination efficacy, both in cell line–derived xenograft and patient-derived xenograft solid tumor models, whether administered locally or systemically." (PMID 33823905, 2021). "The TGF-β receptor II (TGFBR2) depleted CAR-T cells by CRISPR/cas9 promoted tumor elimination efficacy of CAR-T cells both in vivo and in vitro, which provides a novel method to improve CAR-T cells’ function in the TGF-β-rich tumor environment and promote CAR-T cells’ efficacy in solid tumors." (PMID 35111663, 2021). "TGFBR2 also blocked tumor growth in vivo by targeting the miR-645/TGFBR2 axis." (PMID 34381772, 2021). "Three tumor-associated genes, zinc finger and BTB domain-containing 16 (ZBTB16), peroxisome proliferator activated receptor gamma (PPARG), and transforming growth factor beta receptor 2 (TGFBR2), were downregulated with copy number variation (CNV) loss." (PMID 33414372, 2021). "Besides, the expression of TGFBR2 was aberrantly declined in CRC tumor tissues at both mRNA and protein levels." (PMID 34381772, 2021). "Furthermore, it upregulated TGFBR2, increasing the possibility of iTreg conversion within the tumor." (PMID 33602930, 2021). "TGF-beta receptor II (TGFBR2) was proved as a tumor suppressor in CRC." (PMID 34381772, 2021). "From the GSE45216 dataset (the largest dataset), TGFBR2 becomes progressively more underexpressed in the transition from normal skin through AK to cSCC, consistent with the previous studies that have demonstrated a key role for TGFBR2 in TGFβ tumor‒suppressive function." (PMID 33482222, 2021). "Previous findings all maintained that TGFBR2 played an anti-tumor role in CRC." (PMID 34381772, 2021). "Previous studies have already proved the regulation function of SMAD2, SMAD4, and TGFBR2 in cancers, and these genes were also found related with miRNAs that strongly correlated with tumor features, indicating the potential function and clinical utility in immunotherapy." (PMID 34722540, 2021). "TGFBR2 methylation was inversely correlated to its expression in tumor samples." (PMID 32046777, 2020). "Based on the RNA-seq data, TGFBR2 was downregulated in tumor relative to normal tissue samples." (PMID 32046777, 2020). "In this study, the transforming growth factor-β (TGF-β) receptor type II gene (TGFBR2), a key mediator of TGF-β signaling which has been implicated in ESCC carcinogenesis, was identified as a putative tumor suppressor in ESCC based on WGBS of paired and unpaired ESCC tissues." (PMID 32046777, 2020). "To validate whether the expression of TGFBR2 could prevent the tumor progression, we constructed the TGFBR2 overexpression tumor cells in KYSE-150 and KYSE-30." (PMID 32046777, 2020). "TGFBR2 was a putative tumor suppressor gene in the TGF‐β signaling pathway." (PMID 30761256, 2019). "The critical role of altered H19 expression, TGF-β signaling, and ECM deposition in the pathogenesis of UFs is further underscored by findings from genome-wide association studies revealing SNPs in H19, TGFBR2, and GRAF1 that affect both the risk and tumor size of UFs." (PMID 31089260, 2019).
tumor (continued). "Comparison of the 8-week Pten;Tgfbr2 tumors and Pten single mutants at both ages revealed largely overlapping gene expression changes, although changes in these samples were quite variable, possibly due to the mix of normal and tumor tissue at this early age." (PMID 29782499, 2018). "Furthermore, as the tumor cells secrete TGFβ, deletion of TGFβ receptor 2 (Tgfbr2) within the tumor is demonstrated to increase CXCL1/CXCL5 –CXCR2 chemokine and chemokine receptor signaling." (PMID 29966014, 2018). "Therefore, a correlation analysis using gene expression data from a 51 cell line panel was performed to identify genes that are positively coexpressed with TGFBR2 in tumor cells." (PMID 30004628, 2018). "Therefore, we studied the relationship between radiation-induced tumour EndMT and tumour-irradiation responses in EC-specific Tgfbr2-knockdown (EC-TGFβR2KD) mice (Tie2-Cre;Tgfbr2flox/+)." (PMID 30504836, 2018). "However, our data strongly suggest that TGFBR2-dependent reprogramming of exosomal cargo can convey MSI tumor cell-specific biological properties to specific target cells." (PMID 28376875, 2017). "This indicates the tumor-suppressing role of the TGFBR2 gene, and the reduction of its mRNA level may confer a resistance to targeted inhibitors by relapsing tumor growth and proliferation." (PMID 28288164, 2017). "Because this strategy might not only strengthen the telomerase dependent pathway of hTERT to control tumor, but also fill in the gaps which are produced by TGFBR2 that controls tumor only dependent on telomerase." (PMID 28195144, 2017). "Orthotopic transplantation of rescued CD34+ SCC cells resulted in a two-fold delay in tumor latency compared to Tgfbr2 cKO CD34+ SCC cells infected with the empty vector, although all mice eventually developed tumors due to the inefficient infection rate of the rescue vector." (PMID 28219480, 2017). "TGFBR2 had the highest median expression levels in the Normal-like subtype, which was in concordance with the result that TGFBR2 was significantly down-regulated in the tumours compared with their adjacent normal tissues." (PMID 26703884, 2015). "Thus the TGFBR2-based signature implicates TGF-β in the suppression of local inflammation in the tumor microenvironment, whereas ours highlights tumor cell-autonomous effects of TGF-β on tumor cell proliferation and differentiation (see later)." (PMID 24890385, 2014). "However, instead of detecting gross changes of steady state protein glycosylation levels, our metabolic labeling experiments indicate that the sialylation of de novo glycoproteins appears to be regulated by TGFBR2 signaling in this MSI tumor cell model system." (PMID 23468914, 2013). "In order to overcome the transient nature of this expression system and to allow for a more detailed analysis of these TGFBR2-mediated glycan alterations and its associated downstream signaling effects, we have herein generated the HCT116-TGFBR2 MSI tumor cell line model system." (PMID 23468914, 2013). "In addition, we found another tumor suppressor, TGFBR2, which was down-regulated in both CRC and cancer-adjacent tissues." (PMID 22905095, 2012). "In CRC, TGF-β may induce growth inhibition of cancer cells, and TGFBR2 was a tumor suppressor protein that is required for TGF-β signaling." (PMID 22912877, 2012). "This in turn leads to frameshift mutations in microsatellites, which might contribute to the malignant transformation of tumor cells when located in the coding sequences of tumor suppressor genes like the TGFBR2 (TGF-β receptor type 2)." (PMID 20696052, 2010). "Decreased expression of TGFBR2 found in NPC may block this important pathway of tumor-growth inhibition and promote the NPC malignant transformation." (PMID 18570662, 2008).
tumor (continued). "To better understand the way in which the Tgfbr2 deletion affected local immune events that contributed to the observed tumor dormancy phenotype, we used spectral flow cytometric profiling of immune cells in the lungs of tumor-bearing Tgfbr2MyeKO and control mice." (PMID 40568095, 2025). "This included hypermethylation of negative TMRs associated with tumour suppressor genes, such as TGFBR2 and SMAD3, as well as loss of methylation at negative TMRs for the oncogenes ERBB3 and SND1 and for PTPN13, which is described as having both oncogenic and tumour suppressor roles." (PMID 41036619, 2025). "We also show that the correlation of this immunosuppressive signature with TGFBR2 and the mesenchymal state is conserved in a variety of systemic cancers, suggesting that the findings from this study may be applicable to multiple tumor types." (PMID 40277917, 2025). "Interestingly, TGFBR2 was downregulated in tumor-embedded CD8 T cells." (PMID 39639369, 2024). "Indeed, TGFBR2 expression was significantly lower in tumours with non-wild-type allele lengths for this eSTR (two-sided T-test, P-value = 0.0018), consistent with nonsense-mediated decay of the transcript." (PMID 38336885, 2024). "Notably, positive correlations were found with dendritic cells, CD4+ T cells, and neutrophils, suggesting that TGFBR2 may play a significant role in enhancing the immune regulatory network within the LUAD tumor microenvironment." (PMID 39364312, 2024). "The loss of TGF‐β signalling in Tgfbr2 knockout cancer cells leads to increased TGF‐β activation in the tumour stroma of mouse models, mediating fibroblast activation, which ultimately transforms the tumour into a fibromyxoid state and results in a T‐cell exclusion phenotype." (PMID 39350478, 2024). "Therefore, miR-17-5p and TGFBR2 have a necessary relationship with tumor immunity." (PMID 35241117, 2022). "MiR-17-5p by targeting TGFBR2 could have an impact on the tumor microenvironment." (PMID 35241117, 2022). "However, overexpressed ADAMTS9-AS1 and silencing TGFBR2 together could reverse this regulatory effect (p < 0.05), indicating increased tumor proliferation." (PMID 34900984, 2021). "Moreover, TGFBR2 participates in the proliferation and invasion of tumor cells." (PMID 34900984, 2021). "A decreased number of gene copies was also widely observed in EBV(+) LCs, including tumor-associated genes such as zinc finger and BTB domain-containing 16 (ZBTB16), peroxisome proliferator activated receptor gamma (PPARG), and transforming growth factor beta receptor 2 (TGFBR2)." (PMID 34064727, 2021). "Furthermore, the overexpression of TGFBR2 inhibited the tumor growth obviously in vivo." (PMID 32046777, 2020). "In this context, EV proteins that are upregulated by cellular TGFBR2 deficiency are of particular clinical relevance because knowledge about their function and potential interaction partners might provide some clues about their role in MSI tumor biology." (PMID 31454892, 2019). "Furthermore, a tumor-suppressive role for an intact TGFBR2 and signaling pathway was shown in mice." (PMID 30863498, 2019). "Interestingly, tumor cells with low CD34 expression displayed greater tumorigenicity than cells with high CD34 expression in the Tgfbr2 cKO + Hras backskin SCC, whereas we observed a dramatic enrichment for tumorigenicity in CD34+ SCC cells from transition zone tumors." (PMID 28219480, 2017). "At the beginning of cervical cells malignant transformation, TGFBR2 is a tumor suppressor and it could repress the hTERT expression, while at the late period of malignant transformation, TGFBR2 could accelerate hTERT expression to complete malignant transformation." (PMID 28195144, 2017).